COMMD1 (copper metabolism domain containing 1)
Diseases named in the same sentence as COMMD1 in open-access papers (continued):
Sharing a sentence is not in itself a finding about the gene and the disease.
diffuse large B-cell lymphoma (3 papers, 2014 to 2023). "Down-regulation of COMMD1 is associated with poor prognosis in diffuse large B-cell lymphoma." (PMID 36776284, 2023). "Downregulation of COMMD1 was related with a poor prognosis for diffuse large B-cell lymphoma, according to bioinformatics study." (PMID 36776284, 2023). "In diffuse large B-cell lymphoma (DLBCL) high COMMD1 expression is correlated with poor prognosis and is associated with aggressive forms of (DLBCL)." (PMID 27788210, 2016).
head and neck squamous cell carcinoma (3 papers, 2021 to 2024). A squamous cell carcinoma that arises from any of the following anatomic sites: lip and oral cavity, nasal cavity, paranasal sinuses, pharynx, larynx, and salivary glands. "COMMD1 expression was reduced in ovarian cancer, neuroblastoma, prostate cancer, head and neck squamous-cell carcinoma (HNSCC), lung cancer, and colitis-associated cancer progression." (PMID 33768002, 2021).
Hepatitis (3 papers, 2009 to 2021). Inflammation of the liver. "The fact that no intermediate hepatocytes were seen near the activated LPCs in the COMMD1-deficient dogs indicates a minor contribution of these cells to liver regeneration in this stage of hepatitis." (PMID 22879914, 2012). "We identified COMMD1 (previous called MURR1) to be mutated in dogs with the hepatic copper storage disorder, copper toxicosis." (PMID 19802386, 2009). "Longitudinal studies on COMMD1-deficient dogs revealed a progressive development of hepatitis similar to the development of chronic hepatitis in men, yet transplantation of autologous liver organoids with a functional COMMD1 protein did not restore copper excretion in COMMD1 deficient dogs." (PMID 33668783, 2021).
liver cancer (3 papers, 2021 to 2025). An epithelial or non-epithelial malignant neoplasm that arises from the liver. "In conclusion, we have identified COMMD1 as a potential target for liver cancer therapy." (PMID 40109870, 2025). "COMMD10, in contrast to COMMD1, has been extensively studied in the context of liver cancer." (PMID 38817875, 2024).
lymphoma (3 papers, 2014 to 2023). A malignant (clonal) proliferation of B- lymphocytes or T- lymphocytes which involves the lymph nodes, bone marrow and/or extranodal sites. "COMMD1 has an opposing effect on solid tumors versus lymphomas: In patients with solid tumors, decreased COMMD1 expression was related to metastasis and neovascularization, whereas in lymphomas, high COMMD1 expression was correlated with worse prognosis." (PMID 33668783, 2021). "COMMD1 immunoreactivity was primarily localized as perinuclear, granular, cytoplasmic pattern in lymphoma cells, but also in endothelial cells and macrophages with more uniform cytoplasmic staining pattern." (PMID 24625556, 2014). "In the Oncomine database the expression of COMMD1 is increased in lymphomas in comparison to other cancers." (PMID 24625556, 2014). "COMMD1 was elevated in lymphoma, and its level was correlated with poor prognosis." (PMID 38283944, 2023). "In Kaplan-Meier analyses, the patients with high COMMD1 expression had a significantly worse PFS and a trend towards adverse lymphoma associated OS in comparison to the remaining patients with lower COMMD1 expression (5-year PFS 47% vs. 79%, p = 0.005 and 5-year OS 75% vs. 90%, p = 0.081)." (PMID 24625556, 2014). "In lymphomas, the prognostic role of COMMD1 has not previously been established." (PMID 24625556, 2014).
chronic hepatitis (2 papers, 2012 to 2021). An active inflammatory process affecting the liver for more than six months. "COMMD1-deficient dogs develop chronic liver disease and cirrhosis comparable to human chronic hepatitis, although at much higher pace." (PMID 22879914, 2012). "Copper storage in COMMD1-deficient dogs causes chronic hepatitis, fibrosis and cirrhosis causing hepatic failure, portal hypertension, ascites, portosystemic collateral circulation, and hepatic encephalopathy." (PMID 22879914, 2012). "We evaluated COMMD1-deficient dogs as a possible large animal model for chronic hepatitis, in a 42 month lasting longitudinal study." (PMID 22879914, 2012). "The absence of the COMMD1 protein in BT, due to a deletion of exon-2 of the COMMD1 gene, results in a progressive accumulation of copper in hepatocytes leading to chronic hepatitis and cirrhosis." (PMID 22879914, 2012).
Cirrhosis (2 papers, 2012 to 2020). A chronic disorder of the liver in which liver tissue becomes scarred and is partially replaced by regenerative nodules and fibrotic tissue resulting in loss of liver function. "If left untreated, COMMD1 deficiency-related copper toxicosis will result in cirrhosis in 42 months." (PMID 32053895, 2020). "The reticulin stain showed progressive centrilobular fibrosis starting in one of the five dogs at 24 months of age and present in all COMMD1-deficient dogs at 42 months of age, finally resulting in centro-central bridging fibrosis and cirrhosis in three of the five animals (at 42 months)." (PMID 22879914, 2012).
endometrial cancer (2 papers, 2014 to 2016). Primary or metastatic malignant neoplasm involving the endometrium (mucous membrane that lines the endometrial cavity). "COMMD1 is underexpressed in some carcinomas, and low COMMD1 expression has been associated with inferior clinical outcome in patients with endometrial cancer." (PMID 24625556, 2014). "According to the Oncomine database, COMMD1 is differentially expressed in multiple cancer types, and decreased COMMD1 expression in endometrial cancer tissue was shown to correlate with a worse overall survival." (PMID 27788210, 2016).
melanoma (2 papers, 2024 to 2025). A malignant, usually aggressive tumor composed of atypical, neoplastic melanocytes. "Previous research has shown that COMMD1, the most prominent member of the COMMD family, can suppress NF-κB and HIF-mediated gene expression, reducing the aggressiveness of melanoma tumors." (PMID 40109870, 2025).
multiple myeloma (2 papers, 2019 to 2023). "Moreover, individual components of the SCF complex, including Cullin1, S-phase kinase associated protein 2 (Skp2), copper metabolism domain containing 1 (Commd1), and cyclin-dependent kinases regulatory subunit 1(Cks1b) have been linked to Bortezomib resistance in multiple myeloma." (PMID 30885218, 2019). "In Bortezomib-resistant multiple myeloma, however, COMMD1 expression was shown to be elevated." (PMID 36776284, 2023).
myocardial ischemia (2 papers, 2023 to 2025). A disorder of cardiac function caused by insufficient blood flow to the muscle tissue of the heart. "However, the cause of COMMD1 rise due to myocardial ischemia requires additional study." (PMID 36776284, 2023). "This indicates that elevated COMMD1 regulates copper efflux in cardiomyocytes during chronic myocardial ischemia, functioning independently of its interactions with P‐type ATPase transporters." (PMID 40032621, 2025). "Cu concentration is decreased in the ischemic zone of a mouse model of myocardial ischemia, but COMMD1 protein levels are up." (PMID 36776284, 2023).
ovarian tumor (2 papers, 2016 to 2020). "In line with our in vitro data, we found that increased expression of COMMD1 in the nucleus of ovarian tumors is associated with improved response to cisplatin therapy." (PMID 27788210, 2016). "To assess the expression of COMMD1 in ovarian tumors, we first determined the specificity of the anti-COMMD1 antibody in HeLa and HEK293T cell lines, which were stable depleted for COMMD1." (PMID 27788210, 2016). "In the library prepared from ovarian tumor tissue, 5 clones with coding sequences were identified using the HMGB1 bait (C1QA, DAG1, RPL29, RSF1, TGM2), and 6 (COMMD1, MIEN1, PCBP1, TBC1D25, ZFR, ZNF428) were identified with the HMGB2 bait." (PMID 32867128, 2020).
Parkinson disease (2 papers, 2014 to 2021). A progressive degenerative disorder of the central nervous system characterized by loss of dopamine producing neurons in the substantia nigra and the presence of Lewy bodies in the substantia nigra and locus coeruleus. "The effect of COMMD1 on protein aggregation is client-specific as, in contrast to mSOD1, COMMD1 decreases the abundance of mutant Parkin inclusions, associated with Parkinson’s disease." (PMID 24691167, 2014). "Indeed, COMMD1 encodes a scaffold protein involved in the aggregation of misfolded proteins typically observed in Parkinson’s disease." (PMID 34207710, 2021). "Here, we show a client-specific role for COMMD1 on the aggregation of protein species associated with the neurodegenerative disorders SOD1-linked ALS, Parkinson’s disease and Huntington’s disease." (PMID 24691167, 2014). "Next, we assessed whether COMMD1 also affects the aggregate deposition of other aggregation-prone misfolded proteins, such as a Parkin RING domain mutant (C289G) associated with Parkinson’s disease." (PMID 24691167, 2014).
B-cell lymphoma (1 paper, 2016). "Increased COMMD1 expression is also common in primary mediastinal B-cell lymphoma (PMBL) cells lines and in PMBL patients." (PMID 27788210, 2016).
cervical cancer (1 paper, 2024). A primary or metastatic malignant neoplasm involving the cervix. "In summary, we report a new antitumor mechanism by which triptolide disrupted intracellular copper homeostasis and induced cuproptosis in cervical cancer by regulating the XIAP/COMMD1/ATP7A/B axis." (PMID 39198750, 2024). "In this study, we reported a new antitumor mechanism by which triptolide promotes intracellular copper accumulation by regulating the XIAP/COMMD1 pathway and subsequently induces cuproptosis in cervical cancer cells." (PMID 39198750, 2024). "In summary, we report a new antitumor mechanism of triptolide, which disrupted intracellular copper homeostasis and induced cuproptosis in cervical cancer cells by regulating the XIAP/COMMD1/ATP7A/B axis." (PMID 39198750, 2024). "We demonstrated that triptolide upregulated COMMD1 expression and downregulated ATP7A and ATP7B expression by inhibiting XIAP, thereby promoting intracellular copper accumulation and subsequently inducing cuproptosis in cervical cancer cells." (PMID 39198750, 2024).
cirrhosis of the liver (1 paper, 2021). "As far as copper accumulation is concerned, COMMD1-deficient Bedlington terriers develop severe copper accumulation and pathological changes, ultimately resulting in cirrhosis of the liver." (PMID 33262129, 2021).
colon adenocarcinoma (1 paper, 2011). "We used the human HT-29 colon adenocarcinoma cell line because it expresses both CFTR and COMMD1 endogenously and was previously used for co-immunoprecipitation experiments." (PMID 21483833, 2011).
colorectal tumours (1 paper, 2017). "Using the described ex vivo protocol with patient tumour biopsies, we could show that aspirin also caused increased COMMD1 in 3/4 colorectal tumours, again potentially identifying patients that would benefit for aspirin therapy." (PMID 28931905, 2017).
cystic fibrosis (1 paper, 2011). Autosomal recessive disorder caused by pathogenic variants in the CFTR gene (cystic fibrosis transmembrane conductance regulator), which encodes a chloride and bicarbonate channel expressed in epithelial cells, and follow the diagnosis criteria. "Thus, increasing COMMD1 expression may provide an approach to simultaneously inhibit ENaC absorption and enhance CFTR trafficking, two major issues in cystic fibrosis." (PMID 21483833, 2011).
diabetic (1 paper, 2024). "Upstream regulator analysis suggested COMMD1, HIF1A, EGLN, PIK3R1 and MTORC1 as major upstream regulators for the phase shifts, while HSP90B1, YWHAZ, CNGA3, COL2A1 and TFRC were identified as the major upstream regulators for the amplitude changes observed in the diabetic retina." (PMID 38039846, 2024).
gastric cancer (1 paper, 2024). A primary or metastatic malignant neoplasm involving the stomach. "Kaplan-Meier (K-M) analysis was conducted for each COMMD gene in gastric cancer tissues, revealing COMMD1 and COMMD10 as significant high-risk factors for overall survival (OS) in gastric cancer patients." (PMID 38817875, 2024). "In comparison to COMMD1/6, the other COMMDs genes exhibited a significant trend of high expression in gastric cancer." (PMID 38817875, 2024). "As depicted in, except for COMMD1 and COMMD6, the remaining COMMD genes included in the study exhibited significant differential expression in gastric cancer." (PMID 38817875, 2024).
Huntington disease (1 paper, 2014). Huntington disease (HD) is a rare neurodegenerative disorder of the central nervous system characterized by unwanted choreatic movements, behavioral and psychiatric disturbances and dementia. "Aggregation of a polyglutamine-expanded Huntingtin, causative of Huntington’s disease, appears unaltered by COMMD1." (PMID 24691167, 2014). "In contrast to mutant SOD1 and Parkin aggregates, COMMD1 has no clear effect on the aggregation of a fragment encoding the N-terminal region of exon 1 of the Huntingtin gene with either 74 or 119 glutamine repeats (HttQ74 and HttQ119) associated with Huntington’s disease." (PMID 24691167, 2014).
hypercholesterolaemia (1 paper, 2016).
ischemic heart disease (1 paper, 2024). "Therefore, we propose that in the early stages of ischemic heart disease, the predominant cellular damage effects in the early stages of injury are primarily attributed to the copper overload in heart, which activate COMMD1 transcription to facilitate compensatory copper efflux." (PMID 38714741, 2024).
ischemic stroke (1 paper, 2021). A stroke disorder caused by obstruction of blood flow to the brain, due to thrombotic (local blood clot formation) or embolic (due to a blood clot or other material traveling from another site) event. "The results demonstrate that impaired HIF-1 transcription activity, due at least partially to overexpression of COMMD1, is associated with the defective cerebral recovery from ischemic stroke in aged rats." (PMID 33716719, 2021).
laminopathies (1 paper, 2023). "The interaction between Lamin A and COMMD1 indicates that COMMD1 may potentially be associated with aging and laminopathies." (PMID 36776284, 2023).
Menkes disease (1 paper, 2020). A usually severe multisystemic disorder of copper metabolism, characterized by progressive neurodegeneration and marked connective tissue anomalies as well as typical sparse abnormal steely hair. "The discovery that COMMD1 and ATP7B interact intracellularly revealed a mechanistic link between COMMD1 protein and copper toxicosis, later confirmed for the Menkes Disease protein ATP7A." (PMID 32903631, 2020).
X-linked intellectual disability (1 paper, 2016). An X-linked intellectual deficiency in which not enough information is known, reported or published to indicate whether a gene causes non-syndromic or syndromic presentations. "We find that patients with X-linked intellectual disability caused by mutations in CCDC22 are hypercholesterolaemic, and that COMMD1-deficient dogs and liver-specific Commd1 knockout mice have elevated plasma LDL cholesterol levels." (PMID 26965651, 2016).
cancer (22 papers, 2011 to 2025). A tumor composed of atypical neoplastic, often pleomorphic cells that invade other tissues. "Genes such as FDX1, CAT, CDKN2A, DLAT, LIPT1, and COMMD1, which are associated with cuproptosis, are crucial for the growth, advancement, and spread of various cancers." (PMID 40109870, 2025). "COMMD1 is the COMMD protein the most cited for its relation to cancer and decreased COMMD1 expression is associated with increased tumor invasion and worse survival." (PMID 33768002, 2021). "The TCGA dataset revealed that COMMD1 expression was higher in HCC tissues than in normal tissues, and the mRNA expression of COMMD1 was significantly associated with patients’ individual cancer stage and tumor grade." (PMID 34493238, 2021). "The exact mechanism underlying this effect, and whether COMMD1 expression levels are associated with the response to platinum-based therapy in cancer patients remains unclear." (PMID 27788210, 2016). "This peptide exerts antiproliferative and cytotoxic effects on cancer cells by interacting with and stabilizing COMMD1, thereby inhibiting the expression of NF-κB-regulated antiapoptotic genes." (PMID 40308609, 2025). "As per the results of the CCK8 assay, in both Huh7 and Hep3B cells, depletion of COMMD1 exhibited an inhibitory effect on cancer cell proliferation." (PMID 40109870, 2025). "COMMD1 plays pleiotropic roles in cancer progression modulating oxidative stress, DNA damage response, as well as NFκB and hypoxia mediated transcription." (PMID 38476765, 2024). "COMMD1 captured our attention it has been confirmed to play a regulatory role in various cancers, indicating its intrinsic regulatory value." (PMID 38817875, 2024). "Together, these data reflect that antimiR200c reduced ROS signaling and activated anti-cancer immune responses while COMMD1-KD upregulated heterotypic pathways including ROS and TGFB with immunosuppression." (PMID 38476765, 2024). "Recently, it has been shown that miRNA-205 can promote an inflammatory response through the regulation of Domain containing copper metabolism (COMMD1) in cancer cells." (PMID 38069307, 2023). "In NSCLC cell lines, COMMD1 was found to promote cancer cell proliferation and COMMD1 depletion by siRNA significantly decreased cell proliferation and reduced NSCLC cell viability." (PMID 33669398, 2021). "The mRNA expression levels of COMMD1–10 were correlated with individual cancer stage: patients with a more advanced cancer stage tended to express higher mRNA levels of COMMD proteins." (PMID 34493238, 2021). "Several studies have reported that COMMD1 inhibits cancer progression through anti-inflammatory activities." (PMID 34493238, 2021). "There has been some disparity in the field regarding the sensitivity of COMMD1-depleted cancer cells to DNA damaging agents." (PMID 33669398, 2021). "The ONCOMINE and the UALCAN databases were used to evaluate the expression of COMMD1–10 in HCC and the association of this family with individual cancer stage and tumor grade." (PMID 34493238, 2021). "Accordingly, constitutional deficiency of COMMD1 leads to broad activation of HIF-1α and embryonic lethality, while its deficiency in cancer cells promotes HIF-1α-dependent gene expression and tumor cell invasion." (PMID 30487795, 2018). "Another member of the COMMD protein family, COMMD1, has also been shown to be decreased in a variety of cancers." (PMID 29050225, 2017). "COMMD1 downregulation in cancer cells induced NF-κB activation and inflammatory responses in cancer cells and the tumor microenvironment." (PMID 28116318, 2016). "In vitro studies revealed that COMMD1 plays a role in sensitizing cancer cell lines to cisplatin, however, the mechanism and its role in platinum sensitivity in cancer has yet to be established." (PMID 27788210, 2016). "Copper metabolism MURR1 domain 1 (COMMD1) protein is a multifunctional protein, and its expression has been correlated with patients’ survival in different types of cancer." (PMID 27788210, 2016).